NGF (nerve growth factor)
Diseases named in the same sentence as NGF in open-access papers (continued):
Sharing a sentence is not in itself a finding about the gene and the disease.
ischemic stroke (continued). "In addition, EA may improve synaptic plasticity in rats with ischemic stroke via protecting synaptic ultrastructure and promoting the levels of NGF, BDNF, GAP-43 and p38 in the ischemic brain's cortex." (PMID 30618558, 2018). "In conclusion, our findings suggest that the NGF rs6330*T and NGFR rs2072446*T minor alleles might be nominated as a risk factor for developing ischemic stroke and NGFR rs734194*G minor allele as a protective against this disease at least in Armenian population." (PMID 29499660, 2018). "Previous studies demonstrated that altered presence of NGF and its receptor (NGFR) are linked to several important processes such as vascular hypertension, atherogenesis and inflammation which are considered to be risk factors for the development of ischemic stroke (IS)." (PMID 29499660, 2018). "The purpose of the present study was to assess the effects of rTMS on the serum concentrations of BDNF, NGF, 5-HT, and 5-HIAA in patients with ischemic stroke." (PMID 40109842, 2025). "Isorhamnetin has been shown to promote neuronal differentiation by potentiating nerve growth factor-induced neurite outgrowth in PC12 cells and to exert cerebrovascular protection in a murine model of ischemic stroke by reducing infarct volume and mitigating oxidative damage." (PMID 40650201, 2025). "Recent clinical trials investigated intranasal NGF delivery in patients with TBI (Phase II, NCT01212679, 2017), or with ischemic stroke (Phase IV, NCT03686163, 2020), but results have not been reported yet." (PMID 40153582, 2024).
myocardial infarction (26 papers, 2009 to 2025). Gross necrosis of the myocardium, as a result of interruption of the blood supply to the area, as in coronary thrombosis. "M2 macrophages suppress ventricular arrhythmia caused by sympathetic nerve remodeling after myocardial infarction by reducing the expression of NGF found that Sinapic acid (SA) stimulated the PPARγ pathway with concentration-dependent to promote M2 polarization and reduce NGF." (PMID 39104386, 2024). "This is the first study to confirm that BBR can reduce the risk of arrhythmia attacks after myocardial infarction by inhibiting the TGF-β1-induced transformation of CFS into myofibroblasts and directly inhibiting the secretion of NGF by myofibroblast cells." (PMID 40496730, 2025). "Conversely, excessive NGF driven sympathetic sprouting can be maladaptive after myocardial infarction." (PMID 41471293, 2025). "Multiple studies have shown that NGF is a key cytokine involved in the sympathetic activity of arrhythmias after myocardial infarction." (PMID 40496730, 2025). "In patients with HF and in rats with post-myocardial infarction HF, NGF expression decreases due to the dysfunction of cardiac sympathetic nerve endings." (PMID 39502198, 2024). "One previous study demonstrated that stellate ganglionic nerve sprouting and density are elevated at one to four weeks after coronary artery ligation-induced rabbit myocardial infarction, which is mediated by nerve growth factor." (PMID 36362099, 2022). "Our results indicated that E2 polarized macrophages into the M2 phenotype by inhibiting the superoxide pathway, leading to attenuated nerve growth factor‐induced sympathetic hyperinnervation after myocardial infarction." (PMID 35514058, 2022). "A number of experiments have verified that the expression of GAP43 factor and NGF increase at the same time, indicating the rapid growth of related nerves, especially after myocardial infarction." (PMID 34471416, 2021). "NGF and GAP43 are nerve growth factors, which can cause excessive regeneration and uneven density of cardiac nerves after myocardial infarction while Sema-3A is a nerve growth inhibitor, which can inhibit the excessive growth of sympathetic nerves." (PMID 34471416, 2021). "NGF is upregulated in cardiac hypertrophy and also after myocardial infarction in a canine model, leading to heterogeneous hyperinnervation." (PMID 27590099, 2016). "The relevance of this to arrhythmia was demonstrated by NGF infusion after myocardial infarction which resulted in an increased incidence of ventricular arrhythmia and sudden cardiac death." (PMID 27590099, 2016). "NGF gene therapy accelerates cardiac repair following myocardial infarction or type 1 diabetes, further establishing TrkA as cardioprotective." (PMID 23437390, 2013). "Activated fibroblasts (myofibroblasts) isolated from myocardial infarction rat hearts exhibited significantly higher mature NGF expression than normal fibroblasts and also promoted PC12 cells differentiation." (PMID 24244423, 2013). "NGF promotes cardiac repair following myocardial infarction." (PMID 41516081, 2025). "On the other hand, NGF is expressed by ischemic myocytes and may also increase cell survival during acute myocardial infarction." (PMID 41516081, 2025). "This indicates that BBR may reduce sympathetic nerve remodeling by inhibiting the secretion of NGF from myofibroblasts, thereby further reducing the incidence of arrhythmias after myocardial infarction." (PMID 40496730, 2025). "As demonstrated, the use of agonists or antagonists of the NGF receptor (TrkA) or the NGF gene transport may improve angiogenesis and cardiomyocytes survival, thus promoting the cardiac response after a few weeks post-myocardial infarction." (PMID 36798942, 2023).
myocardial infarction (continued). "The combined treatment of anisodamine-tirofiban in patients with acute myocardial infarction after percutaneous coronary intervention (PCI) can recover NGF and ESM-1 related proteins, improve postoperative myocardial perfusion, and accelerate the recovery of cardiac function." (PMID 36246689, 2022). "Furthermore, NGF, as a novel biomarker in myocardial infarction, plays a vital role in the differentiation, survival, and synaptic activity of sympathetic nerves after myocardial I/R." (PMID 31287006, 2019). "Similarly, activated myofibroblasts isolated from the cardiac ischemic area following myocardial infarction, overexpressed NGF correlating with sympathetic anarchical hyperinnervation in the tissue scar." (PMID 24244423, 2013). "Beyond actions on cardiomyocytes per se, it has also been shown that NGF may exert beneficial actions via vascular effects, including the stimulation of angiogenesis following myocardial infarction." (PMID 23300892, 2012). "Given that ET-1 is strongly induced in myocardial infarction and cardiac hypertrophy, the ET-1/NGF pathway may also be involved in NGF upregulation and nerve regeneration in pathological hearts." (PMID 21037846, 2009). "This research highlights key genes associated with mitochondrial oxidative stress—VCL, ABCB1, JAK2, KDR, NGF—that show differential expression in DCM and myocardial infarction." (PMID 40217309, 2025). "To further explore the role of BBR in arrhythmias after myocardial infarction, we used the molecular docking technique and found that BBR has the highest binding energy with NGF, resulting in a more stable binding." (PMID 40496730, 2025). "NGF rapidly released and the concentration of NGF and GAP43 in the area around the infarction increased immediately after myocardial infarction." (PMID 34471416, 2021). "In this study, YQHX can significantly regulate nerve remodeling related factors and reduce the protein content of TH, NGF, and GAP43 in the marginal area of infarction and the stellate ganglion in rats with myocardial infarction." (PMID 34471416, 2021). "The protein content of NGF and GAP43 in the marginal area of the MI group increased significantly while the protein level of Sema-3A decreased 28 days after myocardial infarction." (PMID 34471416, 2021). "This study explores the effects of anisodamine-tirofiban combined therapy on cardiac function and the expression of serum NGF and ESM-1 in patients with acute myocardial infarction who underwent percutaneous intervention (PCI), to provide a scientific basis for clinical treatment." (PMID 36246689, 2022). "We have also shown that, in non-diabetic mice with myocardial infarction, systemic NGF gene therapy promotes detachment of progenitor cells from the endosteal niche through activation of metalloproteinase-9." (PMID 31016359, 2019). "Nerve growth factor (NGF) is involved in nerve sprouting, hyper-innervation, angiogenesis, anti-apoptosis, and preservation of cardiac function after myocardial infarction (MI)." (PMID 24755692, 2014). "In contrast, in a mouse model of myocardial infarction and subsequent sympathetic nerve sprouting, myocardial gene expression of GDNF (estimated by RT-PCR)) was, unlike NGF, virtually unchanged." (PMID 23843937, 2013).
rheumatoid arthritis (26 papers, 2008 to 2025). A chronic, systemic autoimmune disorder characterized by inflammation in the synovial membranes and articular surfaces. "High levels of anti-NGF antibodies have been detected in inflammatory diseases that produce nerve damage, such as lupus, thyroiditis, and rheumatoid arthritis." (PMID 41156731, 2025). "Autoantibodies to NGF have also been found in the sera of some patients with autoimmune diseases such as systemic lupus erythematosus, autoimmune thyroiditis, and rheumatoid arthritis." (PMID 37998739, 2023). "In contrast to our results, the synovial fluid in patients with rheumatoid arthritis is also characterized by elevated NGF levels." (PMID 36627662, 2023). "Nerve growth factor (NGF), an important signaling molecule involved in joint pain, is a key regulator of rheumatoid arthritis pathogenesis, and has recently been implicated in OA pain." (PMID 26577823, 2015). "NGF serum levels are increased in various autoimmune diseases such as systemic lupus erythematosus and rheumatoid arthritis." (PMID 21085492, 2010). "In a rat model of rheumatoid arthritis, intravenous administration of orexin A was shown to reduce pain sensation as well as the serum level of nerve growth factor (NGF), a major mediator of inflammatory and neuropathic pain; effects that are likely attributed to the activation of OX-1 receptors." (PMID 32116534, 2020). "Inhibiting NGF signalling might therefore have particular benefit in patients with inflammatory arthritis pain, including those with rheumatoid arthritis (RA)." (PMID 27145816, 2016). "Indeed, NGF levels are increased in SSc as well as in various others autoimmune disease such as lupus erythematosus, rheumatoid arthritis and primary Sjögren's syndrome." (PMID 21085492, 2010). "In addition, in clinical conditions in patients with chronic pain such as rheumatoid arthritis, cancer pain, or neuropathic pain, the growth factor (NGF and IGF) levels are very high, which results in significant activation of nociceptors, thus enabling the maintenance of chronic neuropathic pain." (PMID 33603820, 2021). "In fact, NGF serum levels have been found to be independent of immunomodulating treatments in other diseases such as systemic sclerosis, rheumatoid arthritis, and primary Sjögren syndrome." (PMID 24223945, 2013). "Concerning rheumatoid arthritis, to our knowledge, the correlation between NGF, BDNF and anti-cyclic citrullinated peptide has not been previously studied." (PMID 24223945, 2013).
cystitis (25 papers, 2007 to 2024). Inflammation of the urinary bladder. "Further studies are required to be carried out to clarify the exact mechanisms underlying the regulation of HCN channels by NGF/TrkA signaling during cystitis." (PMID 37275761, 2023). "Cystitis conditions were associated with increased urothelial NGF expression and decreased TrkA and p75NTR expression as well as altering their co-expression ratio; phosphorylation of ERK1/2 and JNK were also altered." (PMID 37701183, 2023). "It is clear that the upregulation of urothelial NGF is well-implicated in altered urinary function and pain sensation with cystitis, and our findings here further reinforce its importance to the pathophysiology of cystitis." (PMID 37701183, 2023). "BDNF is upregulated throughout the micturition pathway in both humans and rodents with cystitis as a consequence of increased NGF synthesis and its reduction is associated with subjective improvement in IC/BPS patients undergoing treatment." (PMID 37701182, 2022). "Increased levels of NGF in the bladder accompanied the experimental models of SCI causing neurogenic or cyclophosphamide-induced cystitis." (PMID 30653511, 2019). "Thermal hyperalgesia associated with inflammation of the urinary bladder was also shown to be NGF-dependent." (PMID 22654715, 2011). "Cystitis conditions were associated with increased expression of NGF and decreased the expression of its two receptors, TrkA and p75NTR, as well as altering their co-expression ratio; phosphorylation of downstream signaling molecules ERK1/2 and JNK were also altered." (PMID 37701183, 2023). "NGF has been implicated in the peripheral sensitization of nociceptors, contributes to bladder sensory function and the development of referred hyperalgesia in response to urinary bladder inflammation." (PMID 37811396, 2023). "It is possible that the 75 mg/kg dose of CYP used to induce cystitis was insufficient to produce statistically evident increases in NGF expression in the present study." (PMID 37701183, 2023). "Nevertheless, our results demonstrate a clear reduction in urothelial p75NTR expression with cystitis, highlighting the complexity of NGF signaling in the bladder and the necessity of its thorough characterization in models of cystitis." (PMID 37701183, 2023). "NGF expression in the urothelium was significantly increased following induction of acute CYP-induced cystitis." (PMID 37701183, 2023). "NGF is upregulated in the urine and bladders humans with cystitis, and animal models demonstrate changes in its transcription and expression of NGF throughout the LUT." (PMID 37701183, 2023). "BDNF is also upregulated in micturition reflex pathways in both humans and rodents with cystitis because of increased NGF synthesis." (PMID 37811396, 2023). "Unsurprisingly, accumulating evidence suggests that NGF actions in cystitis are primarily TrkA-mediated." (PMID 37701182, 2022). "TrkA inhibition improved bladder function in the chronic cystitis condition as well, while findings resulting from p75NTR and TrkB inhibition provide further insight into the roles of NGF and BDNF signaling in sustained conditions of bladder inflammation." (PMID 37701182, 2022). "Similar to increased expression of NGF after cystitis, increased expression of TrkA- and TrkB-IR and Trk phosphorylation in bladder afferent neurons has been demonstrated." (PMID 29255407, 2017). "The mRNA-levels of total urinary bladder NGF decreased significantly in acute or chronic cyclophosphamide-induced cystitis compared to control animals." (PMID 26746899, 2016). "The PI3K-Akt-BDNF axis was regulated by endogenous NGF in cystitis and also by retrograde NGF signaling in culture." (PMID 24303055, 2013). "We showed above that endogenous NGF increased BDNF expression in L6 DRG during cystitis, and NGF also activated Akt in L6 DRG." (PMID 24303055, 2013).
cystitis (continued). "After CYP treatment, ERK5 but not ERK1/2 is activated in the DRG suggesting a possibility that NGF retrograde signaling plays a role in primary afferent neuronal activation during cystitis." (PMID 24303055, 2013). "BDNF up-regulation in the L6 DRG was triggered by endogenous nerve growth factor (NGF) because neutralization of NGF with a specific NGF antibody reduced BDNF levels during cystitis." (PMID 24303055, 2013). "NGF neutralization in cystitis animals reduced Akt activity suggesting that activation of the Akt pathway was regulated by NGF in vivo." (PMID 24303055, 2013). "The neutralizing NGF antibody also subsequently reduced cystitis-induced up-regulation of the serine/threonine kinase Akt activity in L6 DRG." (PMID 24303055, 2013). "Consistent with this notion, our results show that in cystitis endogenous NGF facilitates CREB activation in primary sensory neurons because NGF antibody treatment blocks cystitis-induced CREB activation in L6 DRG." (PMID 22742729, 2012). "There are also parallel decreases in the CGRP expression along with CREB activation in DRG neurons co-expressing both molecules following NGF antibody treatment of the cystitis animals." (PMID 22742729, 2012). "Cystitis-caused increases in the number of L6 DRG neurons co-expressing CGRP and phospho-CREB were also attenuated by anti-NGF treatment." (PMID 22742729, 2012). "Increased NGF expression is directly involved in the emergence of bladder-related nociceptive responses in cystitis." (PMID 23028581, 2012). "Blockade of NGF action in vivo not only attenuates cystitis-induced CREB activation and CGRP expression in the DRG but also reverses cystitis-induced increases in micturition frequency." (PMID 22742729, 2012). "The present study along with previous publications demonstrates that NGF is a critical endogenous mediator in cystitis-induced bladder sensory hyperactivity." (PMID 22742729, 2012). "Cystitis-induced CGRP expression in L6 DRG is triggered by endogenous nerve growth factor (NGF) because neutralization of NGF with a specific NGF antibody reverses CGRP up-regulation during cystitis." (PMID 22742729, 2012). "This is particularly relevant as in inflammatory conditions, such as cystitis, NGF levels increase and contributes to altered pain states and bladder overactivity." (PMID 22654715, 2011). "CYP-induced cystitis alters NGF and receptor expression in urinary bladder, dorsal root ganglia and major pelvic ganglia." (PMID 17725832, 2007). "Experimentally-induced cystitis induces bladder overactivity and increases bladder NGF protein and transcript." (PMID 17725832, 2007). "Increasing evidence indicates that NGF actions in cystitis are primarily TrkA-mediated." (PMID 37701183, 2023). "Previous studies have examined changes in NGF signaling, which is notably complex and tissue- and context-specific, sporadically at the level of the whole bladder across various species and models of cystitis." (PMID 37701183, 2023). "The expression level of p75NTR was significantly elevated in the rat bladder with CYP-induced cystitis, and blockade of NGF/p75NTR signaling by intravesical instillation of PD90780 induced and aggravated bladder hyperreflexia in control and CYP-treated rats, respectively." (PMID 37275761, 2023). "Both TrkA and p75NTR inhibition affected the activation of signaling pathways downstream of TrkA, supporting the hypothesis that NGF actions during cystitis are primarily TrkA-mediated." (PMID 37701183, 2023). "A preponderance of evidence from both humans and animal models implicates NGF in cystitis." (PMID 37701183, 2023). "NGF-immunoreactivity was intense and present throughout all layers of the epithelium in the women with idiopathic sensor urgency, whereas the patients with chronic cystitis showed weaker staining and irregular distribution within the epithelium." (PMID 33692976, 2021).